SUMO2 (small ubiquitin like modifier 2)
Diseases named in the same sentence as SUMO2 in open-access papers (continued):
Sharing a sentence is not in itself a finding about the gene and the disease.
tumor (25 papers, 2015 to 2025). "Momordin Ic (MC), an SENP1 inhibitor, enhances SUMO2-pH3(Ser10) cytoplasmic accumulation in normoxic normal, high-glucose and hyper-osmotic conditions, thereby causing M-phase arrest and death of tumour cells." (PMID 36980166, 2023). "The upregulation of SUMO2 protein was also observed in the residual tumor tissue with IHC staining, and an increased level of conjugated-SUMO2 was observed in the Western blot test." (PMID 38890737, 2024). "Meanwhile, negligible change of SUMO2/3 staining was observed in tumor tissues after USP34 silencing." (PMID 38167292, 2024). "Mitotic-phase arrested tumour cells, in acute hypoxia, show extensive cytoplasmic aggregates of SUMO2 modified pH3(Ser10) due to liquid–liquid phase separation (LLPS)." (PMID 36980166, 2023). "While future studies aimed at answering this question are likely to provide interesting insights into SUMO function and regulation, the predominance of SUMO2 in tumor cells makes it the ideal SUMO paralog target for anti-tumor therapeutics." (PMID 36759644, 2023). "Since highly hypoxic regions develop in advanced stages of tumour progression, it is noteworthy that significant cytoplasmic colocalization of SUMO2-pH3(Ser10) was identified in HIF1a-positive regions of advanced vs. lower tumour grades." (PMID 36980166, 2023). "Intriguingly, our data suggest that SUMO2 transcripts are even more abundant in tumor-derived cell lines than in normal adult tissues." (PMID 36759644, 2023). "In this study, we found that circRNF13, acting as a tumor suppressor, directly binds to and stabilizes SUMO2 mRNA, to promote SUMO2 protein expression, thereby inhibiting the proliferation and metastasis of NPC." (PMID 34465340, 2021). "The majority of studies have focused on the effects and mechanisms via which DAXX and SUMO-1 interact; however, few have examined changes in DAXX and SUMO-2/3 during tumor development." (PMID 32641734, 2020). "Consistent with an inhibition of SENP1 activity, Mc treatment also lead to the accumulation of SUMO1- and SUMO2/3-modified proteins in PC3 tumor xenografts." (PMID 27449295, 2016). "We found a strong SUMO2/3-positive immunoreactivity in the cytoplasm in the non-tumor tissues of HCC." (PMID 26458400, 2015). "We have observed that both SUMO2/3 and p65 levels were increased in the non-tumor of liver, where they co-localized in the cytoplasm." (PMID 26458400, 2015). "Immunohistochemistry assay showed that SUMO2/3 was remarkably increased in the adjacent non-tumor tissues, compared with that in the tumor tissues, and SUMO2/3 was mainly localized in the cytoplasm." (PMID 26458400, 2015). "Double-labeled immunofluorescent assay showed that SUMO2/3 was co-localized with p65 in the cytoplasm in the non-tumor tissues." (PMID 26458400, 2015). "Moreover, the differentially expressed genes (DEGs) analysis revealed that Sumo2 was significantly up-regulated in residual tumor following iRFA in HCC." (PMID 38890737, 2024). "The extensive colocalization of pH3(Ser10) with SUMO2 in the cytoplasm of tumour cells exposed to acute hypoxia prompted us to explore whether pH3(Ser10), a master mitotic driver, is a novel substrate of SUMO2." (PMID 36980166, 2023). "However, we extracted the nuclear lysates from tumour cells in HG and HG-HO hypoxic and normoxic conditions, and via co-immunoprecipitation with the SUMO2 antibody, profiled the SUMOylation states of pH3(Ser10) that managed to enter the nucleus." (PMID 36980166, 2023). "Western blotting assay also showed SUMO2/3 was significantly increased in the para-tumor." (PMID 26458400, 2015). "By measuring SAE2 proteins in tumor lysates, we observed that Dox treated SAE2 shRNA tumors have a decreased level of SAE2, associated with lower levels of UBC9-SUMO thioester and SUMO2/3 conjugates, suggesting a functional SUMO inhibition in vivo by our approach." (PMID 25860128, 2015). "However, less than 50% of tumor cells with SUMO2/3 staining had USP34 signals." (PMID 38167292, 2024).
tumor (continued). "In addition, SUMO2 may be a crucial drug target in other tumours too, as indicated by patients' survival plots." (PMID 34715855, 2021). "Because there was a chronic inflammatory response in the non-tumor tissue, we wondered whether the up-regulation of SUMO2/3 is associated with inflammatory response or not." (PMID 26458400, 2015). "Overexpression of SUMO2 in T cells suppresses tumor growth in vivo, linking to higher mRNA levels of IFN-γ and granzyme B in tumor tissues." (PMID 38280996, 2024). "Using the default cutoff value of the GEPIA2 (|Log2FC| cutoff = 1, and q-value cutoff = 0.01), we found that SUMO2 and SAE1 were significantly upregulated in the tumor samples compared with normal livers." (PMID 35859792, 2022). "SUMO-2 and SAE1 were highly expressed in tumor cells, and their low levels correlated with the longer survival of patients with HCC." (PMID 35859792, 2022). "Recent studies found that the dysregulation of SUMOylation contributed to the initiation and development of cancer, and that most SUMO-related genes, including SUMO-2 and SUMO-activating enzyme subunit 1 (SAE1), were overexpressed in many types of tumor." (PMID 35859792, 2022). "We conducted a correlation analysis between the expression of SUMO2 or SAE1 and that of other genes in tumor samples of the TCGA_LIHC and GSE14520 datasets to understand the function of SUMO2 and SAE1 in HCC." (PMID 35859792, 2022). "In these two independent cohorts, both SUMO2 and SAE1 showed a significantly higher expression in tumor samples than in normal ones." (PMID 35859792, 2022). "Immunohistochemistry for SUMO2 and GLUT1 was also performed in mouse tissues, which showed that SUMO2 was expressed at low levels, while GLUT1 was highly expressed in subcutaneous tumor sections of nude mice in the circRNF13 overexpression group." (PMID 34465340, 2021). "circRNF13, acting as a tumor suppressor, directly binds to the 3′-UTR of SUMO2 and prolongs the half-life of SUMO2 mRNA." (PMID 34465340, 2021). "We found that SUMO2 isoform was significantly over-expressed in both primary and recurrent GBM tumour tissues." (PMID 34715855, 2021). "Therefore, we hypothesized that during tumorigenesis and development the human body produces intense stress and defense responses that promote the conjugation between SUMO-2/3 and DAXX, causing DAXX to be transferred from the cytoplasm to the nucleus and increasing the malignancy of the tumor." (PMID 32641734, 2020). "Furthermore, the WB analysis showed that the expression levels of vimentin, PIAS1, P62, cathepsin B and D, SUMO2/3, SUMO1, and CDC42 were lower in the xenograft tumor tissues of Hct116 and LoVo control cells than in the PDCs." (PMID 37833712, 2023). "Consistent with the vital role of SUMO proteins and the UBC9 in SUMOylation, we further demonstrated that similar to SAE1, the expression levels of SUMO1, SUMO2, and UBC9 were upregulated in the HCC tissues compared to their non-tumor paracancerous counterparts." (PMID 33477333, 2021). "Since our analysis suggests that SUMO2 specific conjugation of certain proteins putatively occurs in GBM, pull-down assays in combination with mass spectrometry may enable the identification of such SUMOylated tumour-specific biomarkers in exosomes." (PMID 34715855, 2021). "Thus, we wondered whether Sp1 can be conjugated with SUMO2/3 and be a substrate of SENP3, as we have previously shown that the protein level of SENP3, a SUMO2/3 specific protease, is increased in tumor tissues and under various stress conditions." (PMID 26511642, 2016). "We identified a conserved function of activated SUMOylation in protecting tumor cells against immune destruction, which is further reinforced by a recent genome-wide screening for MHC-I regulators in DLBCL that also identified SUMO2 as a candidate negative MHC-I regulator." (PMID 35499080, 2022).
neurodegenerative disease (2 papers, 2021 to 2022). A disorder of the central nervous system characterized by gradual and progressive loss of neural tissue and neurologic function. "p62 and SUMO2/3 have been described as major components in neuronal inclusions detected in other neurodegenerative diseases, such as FXTAS or SCA7." (PMID 35740026, 2022). "Last, enrichment analysis of the SUMO2/3-modified proteins dataset in KEGG pathways also highlight classes referring to brain disorders such as addictions and neurodegenerative diseases." (PMID 34887727, 2021).
cardiac disease (1 paper, 2016). "Studying the effect of SUMO2 in the context of cardiomyocytes is particularly interesting since small ubiquitin related modifiers have been linked to various cardiac diseases in humans." (PMID 27767176, 2016). "In order to assess the pathophysiological relevance of SUMO2 in cardiac disease, we studied the SUMO2-dependent sumoylation status in two different mouse models of cardiac disease, calcineurin transgenic and TAC (Transverse Aortic Constriction) operated mice." (PMID 27767176, 2016).
hematological malignancies (1 paper, 2025). "Recognizing the importance of SUMO2 in other malignancies, TAK-981—a specific SUMO2 inhibitor—has been developed for clinical testing for many solid tumors as well as hematological malignancies." (PMID 40804185, 2025).
SUMO2 also shares sentences with these, for which no sentence is quoted: intervertebral disc degeneration (3 papers); diabetes (2); lung adenocarcinoma (2); Parkinson disease (2); adult T-cell leukemia/lymphoma (1); astrocytomas (1); Ataxia (1); autism (1); brain disorder (1); Brain Tumour (1); carcinoids (1); cardiovascular disease (1); cataract (1); chronic obstructive pulmonary disease (1); dyslipidemia (1); endometrial cancer (1); epilepsy (1); familial cardiomyopathy (1); helminth infections (1); Hypertension (1); Kyphosis (1); laryngeal carcinoma (1); lupus nephritis (1); metabolic disorders (1); microcephaly (1); myocardial ischemia (1); neurological disorders (1); non-Hodgkin lymphoma (1); non-small cell lung carcinoma (1); Obesity (1).
A further 15 diseases each share a sentence with SUMO2 in 1 paper.